IL17A (interleukin 17A)
Diseases named in the same sentence as IL17A in open-access papers (continued):
Sharing a sentence is not in itself a finding about the gene and the disease.
liver (41 papers, 2013 to 2026). "In this study, we find that the expressions of IL-17A and IL-17A-related molecules as well as components of the IL-17A signaling pathway are increased in the fibrotic liver tissues caused by cholestatic liver injury." (PMID 28039485, 2017). "Levels of multiple proteins, such as interleukin-17A, matrix metalloproteinase-10, and fibroblast growth factor-19, differed (fold-change >1.2; false discovery rate <0.05) between ileal versus colonic IBD." (PMID 39495605, 2025). "Novel data have identified TNF-α, IL-17A and IL-6 as crucial link between enhanced activity of immune system and colon carcinogenesis." (PMID 28881574, 2017). "Also, IL-10 was significantly decreased with IFNγ or IL-17A treatments, suggesting a decrease in inhibitory factors concomitant with an increase in cytotoxicity in two GI tumor models." (PMID 33042110, 2020). "Besides, in our series IL-17A+ lymphocytes were also found in a lower proportion in the liver denoting their contribution to the pathogenesis given its relation to liver damage parameters." (PMID 29038590, 2017). "In conclusion, we report previously unrecognized pro-tumorigenic roles for G-CSF in gastrointestinal tumors through inhibition of CD4+ and CD8+ T cell responses by promoting IL-10 and reducing cytotoxic responses in IFNγ- and IL-17A- dependent mechanisms." (PMID 33042110, 2020).
neurodegenerative disease (41 papers, 2015 to 2025). A disorder of the central nervous system characterized by gradual and progressive loss of neural tissue and neurologic function. "IL-17A is also implicated as a key contributor to CNS autoimmune disorders such as MS and neurodegenerative diseases including AD and PD." (PMID 40469524, 2025). "Specifically, Th17 cells, through production of IL-17A acting on various resident cells in the CNS, have been implicated in the pathogenesis of several neurodegenerative diseases." (PMID 40234983, 2025). "Elevated levels of IL-17A and its associated signaling pathways have been observed in patients with neurodegenerative diseases, suggesting a strong link between IL-17A-driven inflammation and disease progression." (PMID 40141149, 2025). "Studies have shown that IL-17A acts on multiple resident cells of the central nervous system, enhances neuroinflammatory response, and plays a pathogenic role in a variety of neurodegenerative diseases." (PMID 35459141, 2022). "To date, most pieces of evidence point to a pathogenic role for IL-17A in the CNS neurodegenerative diseases." (PMID 33132897, 2020). "Although the specific mechanism of IL-17A in neurodegenerative diseases is still controversial, it is generally accepted now that IL-17A causes diseases by activating glial cells." (PMID 33132897, 2020). "Although the specific mechanism of IL-17A in neurodegenerative diseases is still controversial, it is generally accepted that IL-17A causes diseases by activating glial cells." (PMID 33132897, 2020). "IL-17RC serves as an essential subunit of the IL-17 receptor complex and mediates the signal transduction and proinflammatory activities of IL-17A and IL-17F, which have been implicated in autoimmune and neurodegenerative diseases." (PMID 26504591, 2015). "Notably, IL-17A derived predominantly from microglia has also been implicated in the pathobiology of various neurodegenerative diseases such as Alzheimer’s and Parkinson’s’ disease." (PMID 37095162, 2023). "Studies have shown that IL-17A played a pathogenic role in several neurodegenerative diseases." (PMID 35459141, 2022). "While IL-17A’s role in neuro-inflammation is clear, its exact mechanisms in the pathophysiology of different neurodegenerative diseases are still unclear." (PMID 40141149, 2025). "This review examines the relationship between neuro-inflammation and CNS neurodegenerative diseases, with a particular emphasis on the latest research on IL-17A-mediated inflammatory responses in the CNS." (PMID 40141149, 2025). "Although IL‐17A is widely expressed in various neurodegenerative diseases, its expression in DLB has been rarely reported." (PMID 39754303, 2025). "IL-17A is also a key regulator of neuro-inflammation in other neurodegenerative diseases, such as AD and PD." (PMID 40141149, 2025). "Nevertheless, the precise relationship between IL-17A and microglia in neurodegenerative diseases remains uncertain." (PMID 40141149, 2025). "Interleukin-17A (IL-17A), a key pro-inflammatory cytokine, has been increasingly recognized as a critical driver of glial cell activation in neurodegenerative diseases." (PMID 40141149, 2025). "The role of IL-17A’s in neurodegenerative diseases, particularly AD, is still debated; however, it is postulated to promote inflammation in the vascular wall and contribute to coagulation and thrombosis." (PMID 40150012, 2025). "In recent years, there has been a growing interest in the potential role of T helper cell 17 (Th17) and IL-17A in the pathogenesis of neurodegenerative diseases." (PMID 40141149, 2025). "For its part, IL-17A is a cytokine produced mainly by Th17 lymphocytes and has a highly proinflammatory effect, since it participates in autoimmune and degenerative diseases of the central nervous system (CNS)." (PMID 41010614, 2025). "IL-17A-targeting drugs have been appearing as potential immunomodulatory therapies for neurodegenerative diseases, including ALS." (PMID 40234983, 2025).
neurodegenerative disease (continued). "There is limited data on the long-term effects of IL-17A inhibition in these neurodegenerative diseases." (PMID 40141149, 2025). "Although the current evidence suggests that IL-17A inhibition holds promise for treating neurodegenerative diseases, further exploration is needed in several key areas." (PMID 40141149, 2025). "Despite ongoing debates regarding the specific mechanisms of Th17/IL-17A in such diseases, uncovering the molecular pathways of Th17/IL-17A in neurodegenerative diseases can identify appropriate targets for regulating these cellular processes." (PMID 40234983, 2025). "This review highlights the significance of IL-17A in neuro-inflammation and provides insights into drug screening for potential IL-17A-targeted treatments in neurodegenerative diseases." (PMID 40141149, 2025). "The precise mechanisms by which IL-17A contributes to neurodegenerative disease remain under debate." (PMID 40141149, 2025). "IL-17A has emerged as a key player in neuro-inflammatory processes, contributing to the progression of neurodegenerative diseases and CNS BBB disorders." (PMID 40141149, 2025). "In summary, the involvement of IL-17A in neuroinflammation and its effects on various CNS cells render it a critical target for potential therapeutic interventions in neurodegenerative diseases, particularly in MS." (PMID 37680650, 2023). "According to literature, IL-17A regulates the responses of central nervous system resident cells, boosts the neuroinflammatory response, and contributes to the pathogenesis of neurodegenerative diseases." (PMID 38105925, 2023). "IL-17A, produced by Th17 cells, plays a crucial role in human autoimmune, inflammatory and neurodegenerative diseases." (PMID 37680650, 2023). "We also update the findings on IL-17A-targeting drugs as potentially immunomodulatory therapeutic agents for neurodegenerative diseases." (PMID 35459141, 2022). "Recently, there is growing interest in the specific role of T helper Th 17 cells and Interleukin-17A (IL-17A), the most important cytokine of Th 17 cells, in the pathogenesis of the central nervous system (CNS) of neurodegenerative diseases." (PMID 35459141, 2022). "Recently, there is growing interest in the specific role of T helper 17 (TH17) cells and Interleukin-17A (IL-17A), the most important cytokine of Th 17 cells, in the pathogenesis of the CNS of neurodegenerative diseases." (PMID 35459141, 2022). "The impact of medicinal plants on the level of interleukin-17A (IL-17A) in neurodegenerative diseases." (PMID 33132897, 2020). "In this review article, we will focus on the function of IL-17A, in particular the proposed roles of IL-17A, in the pathogenesis of neurodegenerative diseases." (PMID 33132897, 2020). "Although the specific mechanism of IL-17A in neurodegenerative diseases is still controversial, it is generally accepted that IL-17A causes diseases by activating glial cells (especially microglia)." (PMID 33132897, 2020). "In conclusion, IL-17A plays an important role in the pathophysiology of neurodegenerative diseases." (PMID 40141149, 2025). "Additionally, lower IL-17A levels have been observed in the plasma of AD patients compared to healthy controls, suggesting its complex role in the pathophysiology of neurodegenerative diseases." (PMID 40150012, 2025). "However, there is still debate and ambiguity surrounding the function of TH17/IL-17A in neurodegenerative diseases." (PMID 38105925, 2023). "Compared to other neurodegenerative diseases, IL-17A has been mostly studied in MS." (PMID 33132897, 2020). "Therefore, for this review article, we mainly focused on recent studies on IL-17A and its role in neurodegenerative diseases." (PMID 33132897, 2020). "Also, several studies have been reported the impact of medicinal plants on the level of IL-17A in neurodegenerative diseases." (PMID 33132897, 2020). "Studies have shown that IL-17A is involved in the pathogenesis of CNS neurodegenerative diseases." (PMID 33132897, 2020).
neurodegenerative disease (continued). "However, the role of TH17/IL-17A in neurodegenerative diseases is still unclear and contradictory." (PMID 35459141, 2022). "Thus TLR2/4-mediated IL-17A inflammatory signaling is involved in vessel degeneration and revascularization, indicating that modulation of the TLR2/4-IL-17A pathway may be a novel therapeutic strategy for degenerative diseases." (PMID 27297042, 2016). "However, the relationship between IL-17A and microglia in neurodegenerative diseases has not been elucidated." (PMID 33132897, 2020). "Thus, TLR2/4-mediated IL-17A signaling is required in retinal vascular degeneration, indicating that targeting TLR2/4-mediated IL-17A signaling is a novel strategy to promote revascularization and treat degenerative diseases." (PMID 27297042, 2016).
neurological diseases (33 papers, 2012 to 2025). "Taken together, modulating the gut microbiota, which may influence both gut-residing and CNS-associated immune cells that produce IL-17A, represents a promising therapeutic strategy for neurological disorders characterized by chronic inflammation." (PMID 40469524, 2025). "IL-17 is a pro-inflammatory cytokine mainly produced by γδ T cells and Th 17 cells, including six members (IL-17A to IL-17F), which have an important role in neurological disorders." (PMID 38783945, 2024). "Therapeutically, the blockade of IL-17A using monoclonal antibodies (such as secukinumab and ixekizumab) has demonstrated efficacy in diseases like psoriasis and ankylosing spondylitis, suggesting its potential applicability in neurological disorders mediated by neuroinflammation." (PMID 41357230, 2025). "Elevated IL-6 and IL-17A in D2R specific T-cells from subset of patients with SC, TS or PANS were seen compared to controls with neurological disease." (PMID 36061386, 2022). "All the cytokines, with the exception of IL-17A, were present at significantly higher levels in the patients with EVM compared to the patients with “other neurological and non-neurological disorders”." (PMID 31877982, 2019). "Furthermore, all the cytokines/chemokines, with the exceptions of CXCL1, CXCL6, and IL-17A, were detected at higher levels in the patients with LNB, as compared to the patients with “other neurological and non-neurological disorders”." (PMID 31877982, 2019).
respiratory diseases (29 papers, 2013 to 2025). "Our findings contribute to a better understanding in airway EMT and the pathogenesis of respiratory diseases, which are involved with IL-17A and cigarette smoking." (PMID 32000730, 2020). "Our findings contribute to a better understanding in airway EMT and pathogenesis of respiratory diseases, which are involved IL-17A and cigarette smoking." (PMID 32000730, 2020). "We furthermore briefly discuss the possibility to reduce local IL-17A production as a treatment option for respiratory diseases." (PMID 23401702, 2013). "IL-17A cytokines, which are produced by T-helper (Th) 17 cells and also pulmonary macrophages and neutrophils 38, play an important role in the pathogenesis of respiratory disease." (PMID 24497500, 2014). "We here review its role in human respiratory diseases and try to unravel the question whether IL-17A only provides a link between the adaptive and innate respiratory immunity or whether this cytokine might also be locally produced by innate immune cells." (PMID 23401702, 2013). "Thus, our study may contribute to a better understanding in the pathogenesis of those respiratory diseases, which are involved both of IL-17A and cigarette smoking." (PMID 32000730, 2020). "Similarly, other studies have reported a correlation between nasopharyngeal pneumococcal load and disease severity disease, although IL-17A levels were either not measured or associated with respiratory disease outcomes." (PMID 26069966, 2015). "It still remains enigmatic whether the cited respiratory diseases are specifically mediated by local Th17 cells, able to produce several other cytokines, or by the cytokine IL-17A itself, which might be secreted besides by Th17 cells, by several other cell types." (PMID 23401702, 2013).
heart disease (20 papers, 2010 to 2025). "IL-17A is required for the elimination of bacteria, fungi, and T. cruzi, and it is diminished in chagasic patients with established heart disease." (PMID 32973747, 2020). "Taken together, these studies support the hypothesis that CCL20-neutralising antibodies administered to patients with ischaemic heart disease have the potential to suppress the migration of CCR6+ IL-17A-producing γδT cells and improve prognosis." (PMID 28798316, 2017). "However, it is essential to note that correlation does not imply causation, and other factors, such as comorbid conditions or pre-existing heart disease, may also influence both IL-17A levels and EF." (PMID 40599146, 2025). "Despite these observations, Th17 cells do not appear to play a major role in the heart disease of the Stat3C/C mice, since IL-17A neutralization could only protect 25% of the mice and only marginally affected heart infiltration, fibrosis and α-myosin antibody levels." (PMID 23460527, 2013).
intestinal disease (16 papers, 2016 to 2025). "IL‐17A has been implicated in many models of intestinal disease and is considered a biomarker of interest in NEC." (PMID 37697223, 2023). "As A20ZF7 mouse small intestines contain dramatic expansions of SILP Th17 cells and increased tissue-wide expression of IL-17A and IL-22, we next sought to functionally define the potential roles of these cytokines in regulating intestinal disease in A20ZF7 mice." (PMID 40892518, 2025). "Since IL-17A is a signature cytokine produced by Th17 cells, this finding implies that XEGMG can possibly mediate immune responses to lung and intestinal diseases by regulating the Th17 cells." (PMID 37036063, 2023). "Inhibition of IL17A and IL17F in the absence of IFNγ partially protected mice from developing intestinal disease." (PMID 29416538, 2018).
adenocarcinoma (15 papers, 2012 to 2025). A common cancer characterized by the presence of malignant glandular cells. "A similar trend was found in the validation study using independent stage I adenocarcinoma patients; patients with high circulating levels of both IL-6 and IL-17A had an increased risk of poor prognosis." (PMID 28402963, 2017). "Pathway analysis confirmed increased immune activation in CAs compared with AAs, with patients with adenocarcinoma showing increased immune activation pathways including Toll-like receptor pathways and IL17A signaling in CAs compared with AAs." (PMID 36923308, 2022).
neurodevelopmental disorder (10 papers, 2020 to 2025). A behavioral and cognitive disorder with onset during the developmental period that involves impaired or aberrant development of intellectual, motor, or social functions. "This research points to a unique neuroimmune mechanism underlying neurodevelopmental disorders, and IL-17a as a potential therapeutic target for autistic behavioral improvement." (PMID 35726297, 2022).
retinopathy (10 papers, 2012 to 2025). "The oxygen induced retinopathy model was used to examine the role of IL-17A in retinal neovascularization." (PMID 36675261, 2023). "This study was to investigate the effects of Compaximab and raizumab on retinal function and serum interleukin-17A level in retinopathy of prematurity." (PMID 36199782, 2022). "Beyond its effects on endothelial function, inhibiting IL-17A/F may also diminish inflammation, using innovative therapeutic possibilities, notably for diabetic microvascular conditions such as retinopathy." (PMID 40277935, 2025). "Finally, by utilizing the oxygen induced retinopathy model, we determined that IL-17A enhances retinal neovascularization." (PMID 36675261, 2023). "The analysis shows that compared with Combuxil, razumab can attenuate neovascularization retinopathy by inhibiting the expression of IL-17A and act on RORIL-17A axis to reduce the production of VEGF by reducing the proliferation of microglia and Muller glial cells." (PMID 36199782, 2022). "In this study, we unveiled an unprecedented interplay between MSCs, neurons and myeloid cells through which MSCs inhibit aberrant NV and promote revascularization in retinopathy, at least in part, by restoring neuronal Sema3E levels and reducing pathological levels of IL-17A in myeloid cells." (PMID 33553187, 2021). "However, data is scarce related to the role of IL-17A on inducing ER stress in retinopathy." (PMID 33933165, 2021). "There was a positive correlation between the IL-17A level, and the microalbuminuria level, proteinuria level, CIMT, LVMI, and mean 24-h SBP (P < 0.05); however, retinopathy stage and mean 24-h DPB were no correlated with the IL-17A level (P > 0.05)." (PMID 25273526, 2014).
vasculopathy (7 papers, 2014 to 2025). "Inhibition of this ATGL activity via high-throughput sequencing the role GPX4 expression to prevent iron-dependent ferroptosis and IL-17A stimulating angiogenesis via promoting FAO angiogenic vascular disorders are new approaches that requires much attention." (PMID 38841622, 2024). "Notwithstanding, IL-17A, IL-17F, and IL-17E were demonstrated to promote vasculopathy in SSc patients." (PMID 37239000, 2023). "For example, Th17 cells produce the inflammatory cytokine IL-17A, which promotes the proliferation and migration of dermal vascular smooth muscle cells and is involved in the vasculopathy of SSc." (PMID 35686127, 2022). "Th17 cells secrete IL-17A, which could also promote myofibroblast transformation and fibrosis and contributes to vasculopathy, although the issue is still controversial." (PMID 35686127, 2022).
hematological disorders (6 papers, 2012 to 2025). "However, there are few reports on the role that IL-17A plays in hematological diseases." (PMID 32341381, 2020).
inflammatory myopathies (6 papers, 2015 to 2025). "To corroborate these results, we analyzed several inflammatory cytokines like IL-8, TNF-α, IL-1β and IL-17A in the plasma of these inflammatory myopathy patients following IVIG therapy." (PMID 31974400, 2020). "PM/DM are considered as the two most prevalent inflammatory myopathies, which are characterized by the increasing levels of inflammatory cytokines such as IFN-γ and IL-17A." (PMID 32153557, 2020).